DUSP9 (dual specificity phosphatase 9)
Diseases named in the same sentence as DUSP9 in open-access papers (continued):
Sharing a sentence is not in itself a finding about the gene and the disease.
hepatocellular carcinoma (7 papers, 2012 to 2025). A malignant tumor that arises from hepatocytes. "Association of dual‐specificity phosphatase 9 (DUSP9) expression with clinicopathologic features in 63 hepatocellular carcinoma (HCC) cases." (PMID 41383134, 2025). "The murine DUSP9 showed prominent expression in both Hepa1‐6 hepatoma cells and fetal liver tissues compared to healthy adult liver tissues." (PMID 41383134, 2025). "In hepatocellular carcinoma, decreased DUSP9 was reported to promote cell proliferation through the ERK1/2 pathway, which was associated with poor prognosis." (PMID 35163786, 2022). "In opposition with a previous study, Chen and collaborators showed that the forced expression of DUSP9 increased the proliferative capacity of hepatoma cells expressing low level of DUSP9 protein." (PMID 34768967, 2021). "Treatment of hepatoma cells with the ERK kinase antagonist PD98059 totally abrogated the proliferative effect induced by the depletion of DUSP9." (PMID 34768967, 2021). "In our data, we noticed a decreased level of DUSP9 protein following ectopic expression of miR-4510 in hepatoma cells Huh7." (PMID 34768967, 2021). "The depletion of DUSP9 promoted the growth and clonogenicity of hepatoma cells, and the formation of spheroids, while forced DUSP9 expression produced the opposite effect." (PMID 34768967, 2021). "DUSP9 protein was also more expressed in hepatoma cell lines than in immortalized hepatic THLE-2 cells, and in HCC samples than in non-tumoral livers." (PMID 34768967, 2021). "Inversely, hepatoma cell knockout (KO) for DUSP9 proliferated less, had reduced clonogenic capacity, were more sensitive to doxorubicin and harbored higher ERK pathway activity." (PMID 34768967, 2021). "In vivo, forced expression of DUSP9 inhibited the growth of grafted hepatoma cells in mice." (PMID 34768967, 2021). "By interrogating GEO datasets, the authors found that DUSP9 transcript (along with Glypican-3 and α-fetoprotein) was overexpressed in HCCs, fetal livers and human hepatoma cell lines compared to their corresponding non-tumoral counterparts." (PMID 34768967, 2021). "In hepatic tumor cells, DUSP9 negatively regulates the RAS/RAF/MEK/ERK signal by dephosphorylating ERK1/ERK2 and a low level of DUSP9 is correlated with an elevated level of phospho-ERK1/2 in hepatocellular carcinoma (HCC) samples." (PMID 34768967, 2021).
breast carcinoma (6 papers, 2013 to 2025). "For instance, genetic depletion by gene knock-down or digoxin-induced pharmacological inhibition of HIF1 blocks the expression of DUSP9 and induces the loss of its inhibitory effect on the ERK signaling pathway in MDA-MB-231 breast cancer cells." (PMID 34768967, 2021). "This hypothesis, which is in line with the findings of another study, was further supported by an increase in DUSP9 transcript levels in breast cancer patients who received chemotherapy." (PMID 34768967, 2021). "Interestingly, hypermethylation of DUSP9 promoter was also observed in many other solid tumors including bladder urothelial carcinoma, breast carcinoma, cervical squamous cell carcinoma, endocervical carcinoma, lung carcinoma, and pancreatic carcinoma." (PMID 34768967, 2021). "Breast cancer is brought on by the downregulation of the ERK and activation of the p38 signaling pathways through DUSP9,268 inhibition of the MAP/ERK signaling pathway through FLNA." (PMID 38827026, 2024). "MDA-MB-231 cells cultured as mammospheres, which promotes breast cancer stem cell (BCSC) enrichment, expressed a higher amount of DUSP9 protein compared to cells cultured in standard monolayer condition." (PMID 34768967, 2021). "Using a large cohort of breast cancer samples from the TGCA database, the authors found a strong positive correlation between DUSP9 expression and a 10-gene HIF signature in a TBNC-enriched tumor subtype." (PMID 34768967, 2021). "In previous studies, DUSP9 expression was downregulated in tumors and mediated the progression of CRC and breast cancer through the MAPK/ERK signaling pathway, which participated in HCC cell proliferation by regulating glucose metabolism and secretion of inflammatory factors." (PMID 34795217, 2021).
cardiac hypertrophy (5 papers, 2019 to 2025). "Collectively, this evidence implicated a probable contribution of DUSP9 in the pathological mechanism of cardiac hypertrophy." (PMID 34239349, 2021). "After demonstration of DUSP9 deficiency worsened while overexpression ameliorated cardiac hypertrophy in vivo, the gain- and loss-of-function experimentation were executed subsequently to determine the roles of DUSP9 on NRVM in response to cardiac hypertrophy in vitro." (PMID 34239349, 2021). "Collectively, these data indicated that the progression of pressure overload-induced cardiac hypertrophy and heart failure were aggravated in light of DUSP9 absence." (PMID 34239349, 2021). "In accordance with the results of cellular hypertrophy in response to angiotensin II, cardiac hypertrophy exaggeration, fibrosis, and malfunction triggered by pressure overload was evident in the case of cardiac-specific conditional knockout of DUSP9." (PMID 34239349, 2021). "Nonetheless, the role of DUSP9 in pressure overload-induced cardiac hypertrophy and heart failure has yet to be elucidated." (PMID 34239349, 2021). "This study attempted to uncover the potential contributions and underpinning mechanisms of DUSP9 in cardiac hypertrophy." (PMID 34239349, 2021). "These outcomes substantiated the fact that cardiac-specific DUSP9 overexpression was successful in combating cardiac hypertrophy and heart failure in vivo after overload pressure induction." (PMID 34239349, 2021). "Cardiomyocyte-specific DUSP9 transgenic (DUSP9-TG) mice were developed to assist in elucidating the ameliorative effect of DUSP9 in in vivo cardiac hypertrophy development." (PMID 34239349, 2021). "DUSP9 expression was investigated to unravel its potential role in cardiac hypertrophy and heart failure development." (PMID 34239349, 2021). "Our study was oriented to uncover previously unrecognized function of DUSP9 in pressure overload-induced cardiac hypertrophy in both in vivo and in vitro systems." (PMID 34239349, 2021). "To conclude, these findings suggested DUSP9 regulated Ang II-stimulated cardiac hypertrophy through directly binding to ASK1." (PMID 34239349, 2021). "The authors showed that DUSP9 is required to limit pressure overload-mediated cardiac hypertrophy and heart abnormality." (PMID 34768967, 2021). "We continue to explore the functional influence of DUSP9 in cardiac hypertrophy in vivo." (PMID 34239349, 2021). "DUSP9 was involved in progression of cardiac hypertrophy, but this gene may be responsible for progression of CAD." (PMID 31881747, 2019). "Thus, we believe that DUSP9-mediated ASK1-p38/JNK axis may contribute to be a novel molecular mechanism in the onset of cardiac hypertrophy." (PMID 34239349, 2021). "Thus, our study, for the first time, provides evidence that establishes DUSP9 as an intrinsic negative mediator for pressure overload-caused cardiac hypertrophy." (PMID 34239349, 2021). "Moreover, the adverse consequences of DUSP9 absence could be rescued by abolishing ASK1 in response to cardiac hypertrophy after Ang II stimuli." (PMID 34239349, 2021). "Direct binding of dual specificity phosphatase 9 (DUSP9) or N-acetylgalactosaminyltransferase 4 (GALNT4) to ASK1 also reduce its activation, which protects against pathologic cardiac hypertrophy in vitro and in vivo." (PMID 41333012, 2025). "The main findings of this study suggest the potential of DUSP9 in alleviating cardiac hypertrophy at least partially by repressing ASK1, thereby looks promising as a prospective target against cardiac hypertrophy." (PMID 34239349, 2021). "The present study also delineated that by directly interacting with ASK1, DUSP9 regulated p38/JNK but not ERK1/2 in pressure overload-induced cardiac hypertrophy." (PMID 34239349, 2021). "DUSP9 is also an important gene in heart tissue preservation and can counteract the negative effect mediated by pressure overload on cardiac hypertrophy and cardiomyocytes." (PMID 34768967, 2021).
colorectal cancer (5 papers, 2019 to 2025). A primary or metastatic malignant neoplasm that affects the colon or rectum. "DUSP9 is upregulated in colorectal cancer with an association with worse DFS, it promotes cell proliferation and tumor growth in human HCC cells, and its upregulation in triple-negative breast cancer cells correlates with enhanced stemness." (PMID 34830961, 2021). "Otherwise, compared with normal tissues surrounding colorectal cancer, DUSP9 is significantly downregulated in tumor tissues." (PMID 38720884, 2024). "The high methylation status of CpG islands in the DUSP9 promoter may lead to the downregulation of DUSP9 in (colorectal cancer, CRC), while upregulation of DUSP9 can inhibit the proliferation, migration, invasion, and epithelial-mesenchymal transition of CRC cells." (PMID 38720884, 2024).
diabetes (4 papers, 2019 to 2025). "It was also found that diabetes was the only independent variable significantly associated with increased DUSP9 expression in tumors (p = 0.009)." (PMID 40861803, 2025). "The expression of DUSP9 was significantly higher in HNSCC patients with a history of diabetes than in those without." (PMID 40861803, 2025).
Hepatic steatosis (4 papers, 2019 to 2022). Steatosis is a term used to denote lipid accumulation within hepatocytes. "The activities of ASK1 and its downstream target MKK4/7 are induced by DUSP9 deficiency and inhibited by DUSP9 overexpression in hepatic steatosis, indicating that DUSP9 regulates the JNK pathway and related metabolic disorders by dephosphorylating ASK1." (PMID 31817617, 2019). "DUSP9 and DUSP12 retards ASK1 phosphorylation, thereby suppressing MAPKs phosphorylation and subsequent inflammation inhibition, consequently ameliorating hepatic steatosis progression." (PMID 36209205, 2022). "Recently, we have revealed the role of DUSP9 in binding to and dephosphorylating the apoptosis signal-regulating kinase 1 (ASK1), thereby switching off p38 and JNK-axis in the development of hepatic steatosis." (PMID 34239349, 2021). "The functions of dual-specificity phosphatase 9 (DUSP9) in hepatic steatosis and metabolic disturbance during nonalcoholic fatty liver disease were discussed in our prior study." (PMID 34239349, 2021). "According to our current findings, previous studies, and the characteristic of DUSPs family, we demonstrated that the dephosphorylating capacity of DUSPs family members (DUSP22, DUSP3, DUSP9, DUSP12, DUSP14, DUSP26, etc) might be indispensable for its protective role against hepatic steatosis." (PMID 36209205, 2022).
hepatoblastoma (4 papers, 2021 to 2025). Hepatoblastoma (HB) is a malignant hepatic tumor and is the most common pediatric liver cancer. "In hepatoblastoma tissues with heterogeneous DUSP9 expression, cells with high expression of DUSP9 are considered malignant HB‐like cells." (PMID 40271711, 2025). "The results showed that the proportion of heterogeneous DUSP9‐positive cells in hepatoblastoma tissues with poor prognosis was significantly higher than that in hepatoblastoma tissues with good prognosis." (PMID 40271711, 2025). "Due to the high heterogeneity of hepatoblastoma, the expression distribution of DUSP9 and GPC3 exhibited both homogeneity and heterogeneity." (PMID 40271711, 2025). "In 2008, DUSP9 was reported to be part of a 16-gene signature discriminating hepatoblastomas classified as C1 and C2 groups." (PMID 34768967, 2021). "Western blot analysis showed the decreased expression of HB‐associated genes like AFP, OCT4, GPC3, and DUSP9 in IGF2 KD HepG2 cells, indicating that decreasing IGF2 could reduce hepatoblastoma stemness." (PMID 40271711, 2025). "RT‐PCR analysis showed the increased expression of HB‐associated genes like AFP, GPC3, and DUSP9, indicating that SREBF2 could enhance hepatoblastoma stemness." (PMID 40271711, 2025). "Additionally, we simultaneously detected the expression levels of IGF2, SREBF2, DUSP9, and LDs in consecutive sections of 16 hepatoblastoma patient tissues." (PMID 40271711, 2025). "The Western blot analysis of IGF2‐treated cells demonstrated increased activation of the IGF2‐related signaling pathway and the increased expression of HB‐associated proteins, including AFP, OCT4, GPC3, DUSP9, and cMYC, indicating IGF2's role in sustaining hepatoblastoma stemness." (PMID 40271711, 2025). "Western blot analysis showed that Fatostain treatment decreased the expression of HB‐associated genes like AFP, OCT4, GPC3, and DUSP9, indicating that SREBF2 inhibition could reduce hepatoblastoma stemness." (PMID 40271711, 2025). "Interestingly, ginkgolic acid was found to be a potent antitumor agent in several solid tumors, suggesting its therapeutic potential for the treatment of cancer This suggests its putative use in tumors overexpressing DUSP9 such as C2 or C2A hepatoblastomas." (PMID 34768967, 2021). "The authors concluded that DUSP9 is a marker of fetal liver and is more specifically expressed by the very undifferentiated oval cells, which is in agreement with the increased expression of DUSP9 in embryonic-derived hepatoblastoma." (PMID 34768967, 2021). "HUH6 and HepG2 cells exhibited stronger transcriptomic activation of AFP, DUSP9, GPC3, DLK1, MYC compared to other non‐hepatoblastoma cell lines." (PMID 40271711, 2025). "MiR-1246 and miR-212 can target the 3′-untranslated region (UTR) of the DUSP9 transcript and reduce its expression in CRC cells and hepatoblastoma-derived HepG2 cells, respectively." (PMID 34768967, 2021). "They first showed that DUSP9 interacts with ERK1/2 kinases in tumor tissues and hepatoblastoma-derived HepG2 cells." (PMID 34768967, 2021). "We first performed a transcriptomic evaluation of the two well‐recognized hepatoblastoma cell lines, HepG2 and HUH6, using Pearson's analysis with gene signatures in the public GSE168997 dataset to elucidate IGF2′′s role in hepatoblastoma (AFP, DUSP9, GPC3, DLK1, MYC, EPCAM, KRT8, and LIN28B)." (PMID 40271711, 2025). "Using the hepatoblastoma-derived and not the HCC-derived cell line HepG2, the authors also showed that the depletion of DUSP9 slightly increased cell proliferation and improved the basal survival of cells in vitro." (PMID 34768967, 2021). "Therefore, unlike the previous studies, DUSP9 may play rather an oncogenic role in a subgroup of hepatoblastoma, and the early fetal origin of C2 tumors again supports a link between DUSP9 and highly undifferentiated tumoral cells such as cancer stem cells or precursors." (PMID 34768967, 2021).
liver cancer (3 papers, 2020 to 2024). An epithelial or non-epithelial malignant neoplasm that arises from the liver. "Altogether, these data show that the precise role of DUSP9 in liver cancers is still a matter of debate and that additional investigations need to be carried out to determine if DUSP9 acts as an oncogene or a tumor suppressor in liver malignancies." (PMID 34768967, 2021). "The same team published a second paper in 2019 reporting the tumor suppressive role of DUSP9 in liver cancer." (PMID 34768967, 2021). "As NASH can lead to malignant HCC, therapies influencing DUSP9 activity could also be beneficial in patients with liver cancer." (PMID 34768967, 2021).
nonalcoholic steatohepatitis (3 papers, 2019 to 2022). "In agreement with the two previous studies, Ye and collaborators reported the protective effect of the ectopic expression of DUSP9 against nonalcoholic steatohepatitis (NASH), the most frequent and pathophysiological form of NAFLD." (PMID 34768967, 2021). "In recent studies, DUSP9 has been revealed to participate in inflammatory responses in the development of nonalcoholic fatty liver disease (NAFLD) and nonalcoholic steatohepatitis (NASH) via p38 and JNK signaling pathways." (PMID 35163786, 2022).
renal carcinoma (3 papers, 2020 to 2025). A carcinoma arising from the epithelium of the renal parenchyma or the renal pelvis. "The role of DUSP9 in renal cancer has been highlighted in several studies and DUSP9 is regularly found to be down-regulated in renal tumors compared to normal tissues." (PMID 34768967, 2021). "They reported for the first time the decreased expression of DUSP9 mRNA in tumor tissues, suggesting the pivotal role of DUSP9 in the development of renal cancer." (PMID 34768967, 2021). "Phenotypically, forced expression of DUSP9 in ccRCC cell lines inhibited cell growth and migration in vitro and impeded tumor growth and size in vivo in a xenograft nude mouse model, thus showing for the first time the tumor suppressor role of DUSP9 in renal cancer." (PMID 34768967, 2021).
gestational diabetes (2 papers, 2019 to 2025). Carbohydrate intolerance first diagnosed during pregnancy. "The aim of the present study was to examine placental levels of DUSP9 mRNA and protein and to investigate the potential role of DUSP9 in the development of gestational diabetes mellitus (GDM)." (PMID 31772940, 2019).
glioma (2 papers, 2021 to 2025). A benign or malignant brain and spinal cord tumor that arises from glial cells (astrocytes, oligodendrocytes, ependymal cells). "In the context of glioma, neuron-derived exosomal miR-200c-3p was shown to reduce the levels of the m6A writer ZC3H13 in microglia, impairing the methylation of dual specificity phosphatase 9 (DUSP9) mRNA, activating the p-ERK pathway, and ultimately inducing microglial M2 polarization." (PMID 39987091, 2025).
melanoma (2 papers, 2021 to 2022). A malignant, usually aggressive tumor composed of atypical, neoplastic melanocytes. "All four DUSPs tested are also found in mouse melanoma cell lines YUMM1.7, YUMM3.3 and YUMMER1.7, a variant YUMM1.7 exposed to UV radiation, with Dusp9 showing upregulation in the YUMMER1.7 cell line." (PMID 35999349, 2022).
nonalcoholic fatty liver disease (2 papers, 2021 to 2022). "Meanwhile, loss of DUSP9 leads to IKK complex excitation in nonalcoholic fatty liver disease (NAFLD), implying that a latent characteristic of DUSP9 crosses multiple inflammatory signals in the liver." (PMID 36789693, 2022).
squamous carcinoma (2 papers, 2011 to 2022). "Moreover, DUSP-9 is known to be associated with squamous cell carcinoma (SCC) and can independently induce SCC." (PMID 21943117, 2011). "DUSP-9 inactivates the target kinases of squamous carcinoma cells by dephosphorylating both the phosphoserine/threonine and phosphotyrosine residues." (PMID 21943117, 2011).
cardiomyopathy (1 paper, 2025). A disease of the heart muscle or myocardium proper. "MiR-194-5p targets DUSP9 and is involved in oxidative stress and mitochondrial dysfunction, exacerbating sepsis-induced cardiomyopathy." (PMID 40041174, 2025).
head and neck cancer (1 paper, 2025). A primary or metastatic malignant neoplasm affecting the head and neck. "Investigating the impact of DUSP9 on immune cells in tumor microenvironment is crucial for elucidating the mechanisms underlying head and neck cancer." (PMID 40861803, 2025).
keloid (1 paper, 2025). An irregularly shaped, elevated mark on the skin caused by deposits of excessive amounts of collagen during wound healing.
lung carcinoma (1 paper, 2021). "This suggested that DUSP9 acts as a tumor suppressor in lung cancer." (PMID 34768967, 2021).